USP17L5 (ubiquitin specific peptidase 17 like family member 5)
Description:
Deubiquitinating enzyme that removes conjugated ubiquitin from specific proteins to regulate different cellular processes that may include cell proliferation, progression through the cell cycle, apoptosis, cell migration, and the cellular response to viral infection.
Tractability: No criterion of Open Targets' tractability assessment is met for any kind of drug.
Gene: Protein-coding gene on chromosome 4 (9,339,403 to 9,340,995, forward strand). Ensembl gene ENSG00000227140.
Subcellular location: Nucleus; Endoplasmic reticulum
Pathways (Reactome):
Metabolism of proteins: Ub-specific processing proteases
Gene Ontology:
Molecular function: cysteine-type deubiquitinase activity
Biological process: regulation of apoptotic process; protein deubiquitination
Cellular component: endoplasmic reticulum; nucleus
Homologues: Paralogues in human: USP17L24 (99% identical), USP17L25 (99% identical), USP17L26 (99% identical), USP17L27 (99% identical), USP17L28 (99% identical), USP17L29 (99% identical), USP17L30 (99% identical), USP17L20 (99% identical), USP17L11 (99% identical), USP17L17 (99% identical), USP17L18 (99% identical), USP17L22 (99% identical), and 59 more.
Diseases named in the same sentence as USP17L5 in open-access papers:
USP17L5 is named in the same sentence as 1 disease in open-access papers, as found by Europe PMC text mining. Sharing a sentence is not in itself a finding about the gene and the disease. The quoted sentences say what the papers report.
breast carcinoma (1 paper, 2015). "We examined USP17 and USP17L5 expression by QPCR in all four breast cancer cell lines after drug exposure." (PMID 26378038, 2015).